PSMC2 (proteasome 26S subunit, ATPase 2)
Diseases named in the same sentence as PSMC2 in open-access papers (continued):
Sharing a sentence is not in itself a finding about the gene and the disease.
tumor (continued). "First, besides inhibited cell proliferation, migration in vitro and inhibited tumor growth in vivo, we found that PSMC2 knockdown remarkably inhibited the DNA damage of SKCM cells." (PMID 34716318, 2021). "Consistently, the data from in vivo experiments were in line with the results of in vitro studies, indicating that PSMC2 knockdown exerted its tumor suppressive function in CCA." (PMID 34499615, 2021). "Subsequently, the statistical analysis of the correlation between the expression of PSMC2 and the tumor characteristics, survival of patients with GBC showed the role of PSMC2 in the development of GBC." (PMID 34016944, 2021). "These analyses showed the expression levels of PSMC2 were significantly upregulated in patients suffering from advanced tumor grades (P < 0.05)." (PMID 34499615, 2021). "For instance, increased expression of PSMC2 was determined in tumor tissues from the p21-HBx transgenic mice." (PMID 27888613, 2017). "In vivo experiments further showed that PSMC2 knockdown suppressed tumor growth." (PMID 35256584, 2022). "Also, a previous study held that increased expression of PSMC2 was determined in tumor tissues from the p21-HBx transgenic mice." (PMID 34716318, 2021). "Of note, PSMC2 has also been identified as a vital factor in tumor development and progression." (PMID 33718159, 2021). "Reviewing previous research, the author demonstrated that PSMC2 knockdown in tumor cells could inhibit tumor development and that PSMC2 was identified as a potential gene related to certain human tumors." (PMID 34413286, 2021). "The influence of PSMC2 knockdown on tumor growth in vivo was evaluated by mice xenograft models." (PMID 33902600, 2021). "In addition, the solid tumors in the shPSMC2 group had a reduced volume and smaller weight, thus highlighting the suppressive effects of PSMC2 silencing on tumor growth (P < 0.001)." (PMID 34499615, 2021). "In conclusion, for the first time, PSMC2 was revealed as a tumor promotor in the development of GBC, which could regulate cell phenotypes of GBC cells through the interaction with GNG4, and maybe a promising therapeutic target in GBC treatment." (PMID 34016944, 2021). "The TMA analysis showed that PSMC2 is closely related to tumor size, and this effect may be due to the influence of PSMC2 on cell proliferation, apoptosis, and necrosis." (PMID 33718159, 2021). "Despite, little attention has been paid to the tumor regulatory functions of PSMC2." (PMID 34294689, 2021). "For example, the previous research reported that PSMC2 depletion in tumor cells could control tumor growth, thereby PSMC2 was considered as a potential gene for the treatment of multiple cancers." (PMID 34499615, 2021). "More importantly, it has come to light that PSMC2 knockdown attenuated tumor growth in vivo." (PMID 33902600, 2021). "More importantly, this study indicated that abnormal expression of PSMC2 might be related to aggressive tumor features, including histological types and TNM stages." (PMID 27888613, 2017). "Furthermore, each classifier identified in our study can serve as a potential marker for CRC, and the effects of these classifiers may be modulated by critical genes such as PSMC2 and CXCL8, which are associated with CRC of different tumor stages." (PMID 38243058, 2024). "Furthermore, downregulation of PSMC2 decreased the levels of Ki67 and suppressed tumor growth." (PMID 35256584, 2022). "Therefore, PSMC2 is also considered to be an important factor in tumor occurrence and development." (PMID 35256584, 2022). "Besides, through statistical analysis, we also indicated that abnormal expression of PSMC2 might be related to aggressive tumor features, such as physiological grade." (PMID 34244472, 2021). "Also, PSMC2 knockdown exerted its tumor suppressive function in vivo." (PMID 33902600, 2021). "Therefore, PSMC2 may act as a tumor promotor in CCA and could be used as a therapeutic target in the treatment of CCA." (PMID 34499615, 2021).
tumor (continued). "All these demonstrated that knockdown of PSMC2 could suppress tumor growth in vivo." (PMID 34294689, 2021). "Moreover, our mechanistic study recognized GNG4 as a potential downstream target of PSMC2, knockdown of which could aggravate the tumor suppression induced by PSMC2 knockdown in vitro and in vivo." (PMID 34016944, 2021). "The results indicated that CDC73, PSMC2, SOCS3, and ETV4 were substantially upregulated in tumor group than that in control group, whereas PLK2 and LMO7 were substantially downregulated in tumor group than that in control group." (PMID 41318472, 2025). "Our study identified four critical DEGs (CXCL8, PSMC2, APP, and SLC20A1) that demonstrated high performance in identifying CRC in diverse populations and ethnicities, covering a range of tumor stages and histologic grades." (PMID 38243058, 2024). "We also identified significantly higher expression levels of PSMC2 in HCC patients with higher levels of T infiltrate and more advanced tumor stages." (PMID 34413286, 2021). "We showed that PSMC2 expression in GBC tissues is significantly higher than that in normal tissues, while high PSMC2 expression was correlated with more advanced tumor grade and poorer prognosis." (PMID 34016944, 2021). "First, the measurement of PSMC2 expression in clinical specimens established the linkage between high expression of PSMC2 and more serious HCC (more serious T infiltrate and more advanced tumor stage)." (PMID 34413286, 2021). "A paired Wilcoxon test of paired tumor tissue and adjacent non-cancerous tissue from 220 cases revealed that PSMC2 protein expression was dramatically upregulated in cancerous tissue compared with adjacent non-cancerous tissue (P < 0.001)." (PMID 33718159, 2021). "To confirm the effects of PSMC2 on tumor growth in vivo, we generated a xenograft model by injecting nude mice with the same number of shPSMC2 or shCtrl MHCC97-L cells to assess the effects of PSMC2 on HCC cell growth." (PMID 33718159, 2021). "Both tumor volume and weight were significantly lower in the shPSMC2 group, thus indicating that the absence of PSMC2 led to an inhibition in tumor growth (P < 0.001)." (PMID 34413286, 2021). "After scarification, the averaged tumor weight of the control mice was extremely heavier than that in silencing PSMC2 group which presented no tumor growth." (PMID 27888613, 2017). "Following the successful construction of a mouse-based model by injection of GBC-SD cells with or without PSMC2 knockdown, the results of in vivo fluorescnece imaging showed markedly weaker total fluorescence intensity, as well as smaller tumor burden, in shPSMC2 group (P < 0.001)." (PMID 34016944, 2021). "There was no tumor growth in the PSMC2 knockdown group was observed in 35 days." (PMID 27888613, 2017).
infection (2 papers, 2017 to 2022). The state of being infected such as from the introduction of a foreign agent such as serum, vaccine, antigenic substance or organism. "Lentivirus-mediated small RNA interference was conducted and suppressed PSMC2 expression levels which were indicated by real-time PCR and western blotting from SaoS-2 cells with five days infection." (PMID 27888613, 2017).
neurological disease (1 paper, 2016). "Some downregulated proteins such as DPYSL2, TPI1, ALDH, and UCHL1 were found to play critical roles in the neurological disease and PSMA1, PSMA3, PSMC2, PSMD11, and UCHL1 in protein homeostasis." (PMID 27857231, 2016).
PSMC2 also shares sentences with these, for which no sentence is quoted: prostate carcinoma (2 papers); skin cutaneous melanoma (2); amyotrophic lateral sclerosis (1); asthenozoospermia (1); autoimmune disease (1); COVID-19 (1); endotoxemia (1); food allergy (1); glottic carcinomas (1); leukemia (1); liver cancer (1); liver cirrhosis (1); malaria (1); Parkinson disease (1); peanut allergy (1); Peri-Implantitis (1); prion disease (1); prostate tumors (1); rectal tumor (1); Sepsis (1); squamous cell carcinoma (1); thalassemia (1).